SLC26A4 (solute carrier family 26 member 4)
Diseases named in the same sentence as SLC26A4 in open-access papers (continued):
Sharing a sentence is not in itself a finding about the gene and the disease.
deafness (continued). "In China, approximately 70% of hereditary deafness originates from four common deafness-causing genes: GJB2, SLC26A4, GJB3, and MT-RNR1." (PMID 38172427, 2024). "In Taiwan, the common deafness-associated genes assessed, in order of prevalence included GJB2, SLC26A4, OTOF, MYO15A, and MT-RNR1." (PMID 38840095, 2024). "The most common deafness gene was GJB2, with c.109G>A as its hotspot variant, followed by SLC26A4, and c.919-2A>G as its hotspot variant." (PMID 38172182, 2024). "In the present study, 2D-PCR was used to detect the GJB2, SLC26A4, GJB3, and MT-RNR1 genes in 116 deaf patients and to explore the diagnosis rate and mutation patterns of four common pathogenic genes for deafness in Changzhou, Jiangsu, China." (PMID 38172427, 2024). "Nineteen deafness genes were linked with vestibular symptoms; the most frequent genes in autosomal dominant and recessive individuals were COCH and SLC26A4, respectively." (PMID 38610765, 2024). "The most common deafness gene was GJB2, with c.235delC as its hotspot variant, followed by SLC26A4 and c.919-2A>G, as its hotspot variant." (PMID 38172182, 2024). "The study examined 9 deafness-causing hotspots in the 4 most common genes: GJB2(c.35delG, c.176del16, c.235delC, and c.299delAT), GJB3(c.538C>T), SLC26A4(c." (PMID 39287240, 2024). "The GJB2 and SLC26A4 genes were the most common deafness susceptibility genes and their mutations accounted for 28.5% [GJB2: 16.6% (71/428), SLC26A4: 11.9% (51/428)] of mutation positive patients in our study." (PMID 36597107, 2023). "Among the 98 deafness-related genes detected in this study, SLC26A4 (62.7%, 32/51), MYO15A (63.6%, 14/22), OTOF (40.0%, 4/10) and PTPRQ (75.0%, 3/4) contained intronic variants." (PMID 36597107, 2023). "It increased probe coverage density for 29 genes (full-length design for GJB2, SLC26A4, and POU3F4 genes) to facilitate Cap-CNV analysis and detection of deafness-associated genes in mitochondrial loop DNA." (PMID 36350814, 2022). "Pathogenic variants in most deafness genes, including GJB2, SLC26A4, OTOF, MTRNR1, COCH, and MYH9, have been associated with favorable outcomes, probably because the pathology is confined to the inner ear." (PMID 36009393, 2022). "The most prevalent deafness genes identified in our cohort include SLC26A4 (22%), GJB2 (13%), MYO15A (6%), and OTOF (6%); whereas those identified in the American patients were GJB2 (36%), SLC26A4 (13%), MYO7A (8%), and MYO15A (8%)." (PMID 36009393, 2022). "To uncover the roles of nuclear gene mutations in deafness, we screened for the mutations in common deafness-associated genes (GJB2, GJB3, GJB6 SLC26A4 and TRMU) in the matrilineal relatives of the HZD055 and HZD510 pedigrees." (PMID 36292680, 2022). "The causative variants in deafness genes were confirmed, namely eight with bi-allelic GJB2 variants, one with bi-allelic SLC26A4 variants, and one with bi-allelic OTOF variants." (PMID 34943631, 2021). "After exclusion of the three most frequently mutated deafness genes in Tunisia: GJB2, TMC1, and SLC26A4 genes, ES was carried out for the index case TNDF182-3." (PMID 34614013, 2021). "In this light, we recruited a series of Chinese Han deaf families that were preexcluded from mutations in common deafness genes GJB2,SLC26A4, and MT‐RNR1." (PMID 32048449, 2020). "In this study, we characterized the clinical features of 12 Chinese Han deaf families in which mutations in common deafness genes GJB2, SLC26A4, and MT‐RNR1 were excluded." (PMID 32048449, 2020). "Recent comprehensive next‐generation sequencing (NGS) analysis has helped clarify genetic epidemiology; i.e., GJB2 is the predominant deafness‐causing gene, with the other common genes being CDH23, SLC26A4, MYO15A, COL11A2, and MYO7A." (PMID 32027099, 2020). "Homozygous variants in the nearby gene SLC26A4 disrupt anion exchange in the inner ear and the thyroid, causing Pendred syndrome (PDS; OMIM 274600), which is the most frequent form of syndromic deafness." (PMID 32295532, 2020).
deafness (continued). "The 12 Chinese probands have been previously excluded for mutations in common deafness genes GJB2,SLC26A4, and MT‐RNR1 by Sanger sequencing." (PMID 32048449, 2020). "Common deafness-associated genes in Taiwanese families, in order of prevalence, included GJB2, SLC26A4, OTOF, MYO15A, and MTRNR1, which are similar to those found in other populations." (PMID 31581539, 2019). "For hereditary deaf patients, extensive research has shown that the most common genes related to deafness include SLC26A4, mitochondrial 12SrRNA and GJB2." (PMID 31127414, 2019). "Firstly, four common deafness‐related genes (GJB2, GJB3, SLC26A4, and mtDNA 12S rRNA) were evaluated for mutations using a microarray kit." (PMID 31250571, 2019). "Common deafness-associated genes in the Taiwanese patients assessed, in the order of prevalence, included GJB2, SLC26A4, OTOF, MYO15A, and MTRNR1, which were similar to those found in other populations." (PMID 31581539, 2019). "From the epidemiological perspective, mutations of three deafness genes: GJB2, SLC26A4, and MT-RNR1, are much more prevalent than those of other genes worldwide." (PMID 30576380, 2018). "The goal of this research is to explore the genetic cause of a Chinese deafness pedigree who was excluded of GJB2, SLC26A4, or MtDNA12SrRNA variants." (PMID 29849560, 2018). "One of the most common hereditary deafness genes is pendrin (SLC26A4), which has been surprisingly shown to exert its strongest effects on cochlear function by expression in the endolymphatic sac during early development." (PMID 29368643, 2018). "In this study, we used NGS technology, which led to the identification of novel alleles in SLC26A4, MYO15A, OTOG, LOXHD1, and TBC1D24 that are associated with deafness." (PMID 30139988, 2018). "In this present study we have used an allele-specific PCR-based universal array designed to simultaneously screen nine deafness associated variants in the GJB2, GJB6, SLC26A4, MT-RNR1 and MTTS genes that are common in patients of European descent." (PMID 28273078, 2017). "The discovery of the involvement of other deafness genes, including FOXI1 (MIM #601093), KCNJ10 (MIM # 602208) and GJB2 (MIM #121011) in combination with SLC26A4 monoallelic mutation has proposed the existence of digenic inheritance pattern in PDS and EVA." (PMID 28222800, 2017). "A hereditary deafness gene mutation screening was performed to identify the mutation sites in four deafness-related genes (GJB2, GJB3, 12S rRNA, and SLC26A4)." (PMID 28335750, 2017). "The function of SLC26A4 also has been explored in Pendrin knockout mice that recapitulate the pathology observed in humans: profound deafness and bulged endolymphatic spaces of the inner ear with striking." (PMID 27997596, 2016). "First, mutations of the common deafness genes GJB2, SLC26A4, and mtDNA 12SrRNA were investigated in the affected family members by sequencing." (PMID 26832775, 2016). "It is interesting to note that the RAI1 gene is absent in the candidate gene list for genes associated with nonsyndromic and syndromic HL whereas OTOF and SLC26A4 are known as deafness-related genes." (PMID 27082237, 2016). "Our previous study performed mutation screening of common deafness genes GJB2, SLC26A4 and MT-RNR1 in seven consanguineous Uyghur families and detected bi-allelic SLC26A4 mutations in three of them." (PMID 26011067, 2015). "SLC26A4 and FGF3, two genes that have been previously reported to be associated with deafness and Mondini malformation, were included in our targeted NGS analysis." (PMID 26011067, 2015). "Mutations in four human SLC26 genes have been found to be associated with congenital and early-onset Mendelian diseases: chondrodysplasias (SLC26A2), chloride diarrhea (SLC26A3), and deafness with enlargement of the vestibular aqueduct (SLC26A4)." (PMID 26375458, 2015).
deafness (continued). "Maintenance of appropriate fluid homeostasis is important, as evidenced by the fact that mutations in genes such as the solute carrier transporter gene SLC26A4 (pendrin) lead to prelingual deafness." (PMID 26375458, 2015). "All patients underwent mutation screening of three common deafness genes: GJB2, SLC26A4 and the mitochondrial 12S rRNA gene." (PMID 26397989, 2015). "In this study, we investigated the genetic etiology of nonsyndromic deafness in four consanguineous and two multiplex Uyghur families in which mutations in common deafness genes GJB2, SLC26A4 and MT-RNR1 were excluded." (PMID 26011067, 2015). "A single mutant recessive gene, SLC26A4(PDS), which encodes the protein pendrin, is considered to be responsible for the goiter and deafness." (PMID 25295090, 2014). "Although TMPRSS3 mutations seem to be less common than GJB2 mutations, TMPRSS3 mutations lead to inheritable deafness, especially when common GJB2, SLC26A4 and 12S rRNA mutations are excluded." (PMID 25474651, 2014). "A preliminary survey of Chinese domestic genetic epidemiology for deafness showed that the GJB2, SLC26A4 and mitochondrial 12S rRNA (MTRNR1) genes are common mutation hot spots in Chinese nonsyndromic hearing loss." (PMID 24348793, 2014). "In China, routine clinical diagnostic tests for deafness have consisted of the GJB2, SLC26A4, and mitochondrial 12S rRNA genes." (PMID 24586623, 2014). "Cord blood was used for the screening of deafness-susceptibility genes, namely the GJB2, SLC26A4 and mitochondrial 12S rRNA (MTRNR1) genes." (PMID 24348793, 2014). "Therefore, association detection of GJB2, SLC26A4 and mitochondrial 12S rRNA was combined with hearing screening to determine the common sites and frequencies of newborn deafness gene mutation, which may be used to develop a more effective and earlier intervention for hearing disorders." (PMID 24348793, 2014). "For example, in hereditary deafness with mutations of specific genes, such as, GJB2, SLC26A4, OTOF, COCH, and MYH9, mitochondrial mutations, CI is expected to provide successful results." (PMID 25373420, 2014). "Defects in SLC26A4, which encodes the anion (chloride/iodide, chloride/bicarbonate) transporter Pendrin, can cause nonsyndromic DFNB4 deafness with enlargement of the vestibular aqueduct (EVA) and Pendred syndrome." (PMID 24341454, 2013). "Probands with mutations in commonly screened deafness genes GJB2, SLC26A4 and MT-RNR1 were pre-excluded by Sanger sequencing." (PMID 23767834, 2013). "Pre-screening of mutations in three common deafness genes, GJB2, SLC26A4 and MT-RNR1, was performed in all 190 deaf probands by Sanger sequencing." (PMID 23767834, 2013). "Mutations in SLC26A4, MYO15A, and CDH23 are also reported to be frequent and important causes of deafness." (PMID 23967202, 2013). "TMPRSS3, MYO15A, GJB2, SLC26A4 were found to be responsible for deafness in autosomal recessive or sporadic families." (PMID 23967202, 2013). "TMPRSS3, MYO15A, GJB2, SLC26A4 were found to be responsible for deafness in autosomal recessive or sporadic families, while TECTA, WFS1, MYH9, EYA1, COL4A5 and COL11A1 were identified as the responsible genes for deafness in autosomal dominant families." (PMID 23967202, 2013). "We focused on the presumably rare deafness genes by pre-exclusion of mutations in three commonly screened deafness genes GJB2, SLC26A4 and MT-RNR1." (PMID 23767834, 2013). "Common mutations, such as c.35delG or c.235delC in GJB2 or p.H723R in the SLC26A4 gene, have been reported in many recessive deafness genes, and usually they are population-specific." (PMID 22899989, 2012). "Studies of an SLC26A4 knockout mouse demonstrate that acidification and enlargement of the scala media are early events in the pathogenesis of deafness." (PMID 21961810, 2011).
deafness (continued). "As a major sensorineural deafness-associated gene that is discovered following the identification of GJB2, SLC26A4 mutation is associated with the dilation of vestibular aqueduct in NSD and accounts for 4-15% of inherited deafness cases." (PMID 21917135, 2011). "The carrier frequencies of deafness-causing mutations in these patients were 35.55% in GJB2, 3.70% in GJB6, 15.56% in SLC26A4 and 8.14% in mitochondrial 12SrRNA, respectively." (PMID 23554706, 2011). "The NGS targeted 4 deafness-associated mutations commonly found in the Taiwanese population, including p.V37I (c.109G>A) and c.235delC of the GJB2 gene, c.919-2A>G of the SLC26A4 gene, and mitochondrial m.1555A>G of the 12S rRNA gene." (PMID 21811586, 2011). "In summary, current data revealed that near half of the patients with NSHL carry deafness-causing mutation in GJB2, GJB3, GJB6, SLC26A4, or mtDNA 12SrRNA genes: 43.57% in China and 50.06% in other countries." (PMID 23554706, 2011). "Studies in Slc26a4−/− mice have provided a basis to understand the spectrum of phenotypes seen in human patients that range from deafness at birth to deafness during childhood." (PMID 21103348, 2010). "We investigated the relationship between pendrin expression and deafness using mice that have (Slc26a4+/+ or Slc26a4+/-) or lack (Slc26a4-/-) a complete Slc26a4 gene." (PMID 17187680, 2006). "We investigated the relationship between pendrin and deafness using mice that have (Slc26a4+/+) or lack a complete Slc26a4 gene (Slc26a4-/-)." (PMID 15320950, 2004). "During the analysis phase, the research team took altitude (low altitude, medium altitude, high altitude), ethnicity (Tibetan, Hui, Han, Salar, Tu, etc.), and genotype (15 loci of 4 common deafness-causing genes: GJB2, SLC26A4, mitochondrial 12SrRNA, and GJB3) as the core dimensions." (PMID 41734195, 2026). "In the Western Romanian population studied, the risk of deafness is given by pathogenic variants in 7 genes included in the panel: GJB2, USH2A, LOXHD1, SLC26A4, USH1C, COL4A4, COL4A3, present in almost 10% of the cohort, therefore representing a significant risk." (PMID 41303398, 2025). "Pathogenic sequence alterations of the SLC26A4 gene, which encodes for the anion exchanger pendrin (OMIM *605646), lead to EVA in the context of autosomal recessive Pendred syndrome (OMIM #274600) or non-syndromic deafness DFNB4 (OMIM #600791)." (PMID 40121402, 2025). "In the sample of patients with NSHL, syndromes such as Pendred syndrome (six in the SLC26A4 gene), deafness, and male infertility syndrome (DIS) (three males and two females with NSHL with bi-allelic gross deletions in the STRC and CATSPER2 genes) were also found." (PMID 36555390, 2022). "SLC26A4 gene is closely associated with EVA and its homozygous mutations or compound heterozygous mutations may cause deafness and strongly affect quality of life." (PMID 35804348, 2022). "Compared with 20 variants in the four genes of traditional testing, the positive rate of expanded screening in 159 variants of 22 deafness related genes increased significantly (65.2% on average), including GJB2 increasing by 97.2%, SLC26A4 by 21%, and MT-RNR1 by 150%." (PMID 34276761, 2021). "This study presents a HL family GCUFAHL38, in which five different deafness genes (GJB2, SLC26A4, CDH23, MPDZ, KCNQ4) rare variants were co-segregating in different configurations, and thus further highlights the genetic complexity of hearing disorders in highly inbred families." (PMID 34946889, 2021). "In the present study, we have also identified the missense/non-sense heterozygous variants in the OTOG p.(Val1813Gly), SLC26A4 p.(Tyr556∗) CDH23 p.(Ala1631Val), GJB2 p.(Arg165Trp), and MYO15A p.(Arg1965His) genes which are predominant to cause deafness among Indian populations." (PMID 34113375, 2021). "SLC26A4 and FOXI1 are also involved in determining syndromic forms of hearing loss with EVA, which are Pendred syndrome and distal renal tubular acidosis with deafness, respectively." (PMID 34562878, 2021).
deafness (continued). "Four other reports from Korea, Japan and China on the genetic predisposition of hearing loss in sporadic individuals included more than 60 participants with moderate to severe or profound deafness, in which they demonstrated SLC26A4 as the major contributor to hearing loss." (PMID 32681043, 2020). "The most frequent causative deafness gene was TMC1 (DFNA36) (3 cases), followed by the next tier of genes (2 cases each) (CDH23, COCH, SLC26A4, TMPRSS3, ATP1A3), and the genes that were detected only once (ACTG1, GJB2, ILDR1, MYO7A, MYO15A, NF2, NLRP3 and SERPNB6)." (PMID 32238869, 2020). "SLC26A4 gene has some genetic variations that are identified to be involved in both non-syndromic deafness related with vestibular aqueduct enlargement and Pendred syndrome, and it is necessary to study molecular confirmation of Pendred Syndrome Gene in diagnosis of these diseases." (PMID 31971949, 2020). "Our previous research showed that the rate of hotspot mutations in common genes correlated with deafness (GJB2, GJB3, 12S rRNA, and SLC26A4) in the Guangxi region was approximately 9%, which was much lower than the rate in a large cohort of the Chinese population." (PMID 32770655, 2020). "With regard to the responsible gene, the most frequent causative gene was GJB2 (29%), followed by SLC26A4 (9%), CDH23 (7%), MYO7A (4%), OTOF (5%), MYO15A (3%), and LOXHD1 (2%), indicating that these deafness genes are typical deafness genes found in the prelingual CI/EAS patients." (PMID 32027099, 2020). "A comparison of the positive diagnostic rate in the common deafness genes (GJB2, SLC26A4, and 12S rRNA) in this case cohort with that in a larger sample (16,456 cases) from our deafness genetic testing center revealed that our sample selection was representative of the Chinese deafness population." (PMID 31541171, 2020). "Biallelic GJB2 and SLC26A4 sequence variations with functional impact could be identified as the genetic determinant of deafness for two and one patient, respectively." (PMID 29320412, 2018). "The authors did not identify any GJB2 mutations, and reported the SLC26A4 c.919-2A>G mutation as the most common deafness mutation in the Mongolian patients." (PMID 30576380, 2018). "Additional mutations in the SLC26A4 gene or other definite molecular cause for deafness were not identified in the monoallelic patients, after exome sequencing." (PMID 29739340, 2018). "In this case study, we postulated that a combination of SLC26A4, GJB2 and SCARB2 heterozygous mutations may be implicated in deafness, whilst DUOX2 compound heterozygous mutations may be contributed towards thyroid dysfunction." (PMID 28222800, 2017). "Recessive mutations in SLC26A4 are associated with Pendred syndrome (PDS, MIM 274600) which combines HL and goiter, and autosomal recessive deafness with enlarged vestibular aqueduct (EVA) (DFNB4, MIM 600791) and/or incomplete partition of the cochlea (i.e. Mondini dysplasia)." (PMID 27082237, 2016). "Cochlear implantation has been reported to offer satisfactory auditory performance to patients with severe to profound deafness caused by mutations in the GJB2 gene, the solute carrier family 26 member 4 gene (SLC26A4), the otoferlin gene (OTOF), or the myosin XVa gene (MYO15A)." (PMID 26308726, 2015). "We identified many well-established deafness mutations (e.g., GJB2 c.235delC, GJB2 p.V37I, SLC26A4 c.919-2A > G, as well as previously un-reported novel mutations (e.g., DSPP c.3264_3265insCGATAGCGG, p.S1088delinsSRX) which we predict to be deleterious to protein functioning." (PMID 25342930, 2014). "Both Slc26a4+/tm2Dontuh and Slc26a4tm2Dontuh/tm2Dontuh mice had normal hearing up to 9 months, indicating that the p.H723R allele does not lead to deafness in mice." (PMID 23755160, 2014).